LINC02408 (long independently transcribed non-coding RNA 2408)
Gene: Long non-coding RNA gene on chromosome 12 (67,443,105 to 67,590,771, forward strand). Ensembl gene ENSG00000203585.
Diseases named in the same sentence as LINC02408 in open-access papers:
LINC02408 is named in the same sentence as 1 disease in open-access papers, as found by Europe PMC text mining. Sharing a sentence is not in itself a finding about the gene and the disease. The quoted sentences say what the papers report.
thyroid cancer (1 paper, 2022). "The expression levels of LINC02471, LINC02408, LOC642484, and ATP6V0E2-AS1 were significantly different between the malignant nodules and paired normal thyroid tissues as in TANRIC thyroid cancer dataset." (PMID 36132147, 2022).